IL33 (interleukin 33)
Diseases named in the same sentence as IL33 in open-access papers (continued):
Sharing a sentence is not in itself a finding about the gene and the disease.
cerebral malaria (22 papers, 2015 to 2025). A sequestration of Plasmodium falciparum in the brain, which can cause coma and/or seizures. "We report here our investigation on the role of a recently discovered cytokine IL-33, in treating experimental cerebral malaria (ECM) in the susceptible C57BL/6 mice." (PMID 25659095, 2015). "Indeed, IL-33-mediated ILC2 expansion has been linked to resistance against cerebral malaria and various intestinal infections." (PMID 39883714, 2025). "In experimental cerebral malaria, administering recombinant IL-33 alongside standard antimalarial drugs markedly improved survival and reduced brain pathology." (PMID 41002937, 2025). "Surprisingly, administration of exogenous IL-33 prevented the development of cerebral malaria by orchestrating a protective immune response through ILC2, M2 macrophages and Tregs." (PMID 39559705, 2024). "Treatment with IL-33 following PbA-induced murine cerebral malaria reduced NLRP3 inflammasome formation and IL-1β secretion in microglia and intracerebral monocytes during the acute recovery phase." (PMID 39548522, 2024). "IL-33 prevents development of cerebral malaria (CM); however, the IL-33/ST2 pathway in mice lessens the pathogenicity of experimental cerebral malaria." (PMID 37375100, 2023). "Murine experimental cerebral malaria studies suggest both protective and deleterious central nervous system effects from alterations in the interleukin-33 (IL-33)/ST2 pathway." (PMID 35800259, 2022). "Studies of experimental cerebral malaria (ECM) in mice using Plasmodium berghei ANKA haveidentified IL-33 and ST2 as key molecules involved in ECM pathogenesis." (PMID 35800259, 2022). "In models of Leishmaniasis and cerebral malaria, IL-33 contributes to T-cell-dependent immune pathology in the skin and brain, respectively." (PMID 33929319, 2021). "Surprisingly, IL-33/ST2 was shown to have potential therapeutic properties via direct administration of IL-33 as well as serving as an etiological component of cerebral malaria pathogenesis." (PMID 32363166, 2020). "IL-33 is a new player in experimental cerebral malaria development because the microvascular pathology was dependent on IL-33/ST2 signaling." (PMID 32599864, 2020). "Taken together, this demonstrates that IL-33 mediated Treg function is important in preventing cerebral malaria, though the exact mechanisms of which remains to be elucidated." (PMID 32363166, 2020). "In an experimental cerebral malaria study, the induction of IL-33 has led to the polarization to the pro-resolutive macrophages of M2 phenotype and forkhead box P3 (Foxp3) Treg cells." (PMID 32599864, 2020). "IL-33-treated mice had lower rates of cerebral malaria through the reduction in the early pro‐inflammatory-type response." (PMID 31662766, 2019). "A specific role of IL-33 has been investigated in cerebral malaria which is the most severe form of neurological complications associated with Plasmodium falciparum infection." (PMID 30515150, 2018). "Increased IL-33 expression is shown in the brains of experimental cerebral malaria (ECM) mice induced by murine Plasmodium berghei ANKA (PbA), which is likely expressed by astrocytes and oligodendrocytes." (PMID 30515150, 2018). "We reported recently the essential role of IL-33/ST2 pathway in experimental cerebral malaria (ECM) development." (PMID 28448579, 2017). "By contrast, it is also reported that increased expression of IL-33 in mice, either by exogenous administration or induced by experimental cerebral malaria, results in microglial activation and IL-1β production, depicting a harmful effect of IL-33/ST2 axis in cognitive function." (PMID 39122454, 2024). "In experimental cerebral malaria, infection triggered a dramatic increase of IL-33 expression in oligodendrocytes via ST2 pathway, and ST2-deficient mice were resistant to parasite induced neuropathology associated with attenuated neuroinflammation and exacerbated neurogenesis." (PMID 39559705, 2024).
cerebral malaria (continued). "In this context, pharmacological inhibition of the IL-1 axis using existing biopharmaceuticals and administration of recombinant IL-33 could offer new prospects to treat cerebral malaria." (PMID 36362246, 2022). "However, a better knowledge of early innate immune responses involving IL-33/ST2 signaling is required before developing new treatment for cerebral malaria targeting IL-33 modulation." (PMID 36362246, 2022). "In a murine model of experimental cerebral malaria induced by Plasmodium berghei ANKA, ST2 deficiency had a protective effect on the cognitive defects induced by excessive inflammation in the brain in relation with high levels of IL-1β induced by IL-33." (PMID 32571430, 2020). "IL-33 produced by oligodendrocytes could further induce IL-1β and inflammatory activity in glial cells, creating a pathological feedback contributing to cerebral malaria." (PMID 32363166, 2020). "Another school of thought is that cell-specific ST2 activity may play a contributory role in the pathogenesis of cerebral malaria in a differentially IL-33 dependent or IL-33 independent manner." (PMID 32363166, 2020). "Nonetheless, these ostensibly diametric findings demonstrate a gap in our understanding of the role of IL-33 in malarial infection, thus highlighting the need for more research to bolster our understanding of this complicated cytokine in the context of cerebral malaria." (PMID 32363166, 2020). "IL-33 plays an important role in the protection of experimental cerebral malaria." (PMID 31662766, 2019). "Moreover, in PbA-induced experimental cerebral malaria (ECM), IL-33 expression is increased in the brain and ST2-deficient mice were resistant to PbA-induced neuropathology." (PMID 31871954, 2019). "IL-33 may interact with the BBB via these ST2+ astrocytes as reported in an experimental cerebral malaria (ECM) model." (PMID 30515150, 2018). "Using the blood-stage PbA (Plasmodium berghei ANKA) model of infection, we show here that administration of the pro-Th2 cytokine, IL-33, prevents the development of experimental cerebral malaria (ECM) in C57BL/6 mice and reduces the production of inflammatory mediators IFN-γ, IL-12 and TNF-α." (PMID 25659095, 2015). "Data reported here reveal a previously unrecognised role of IL-33 in the protection against cerebral malaria by reducing pro-inflammatory cytokines and chemokines production and inhibiting vascular sequestration of infected erythrocytes and inflammatory cells in the brain." (PMID 25659095, 2015). "Here, we highlighted how IL-33 could influence cerebral malaria pathogenesis." (PMID 36362246, 2022). "Given the pleiotropic nature of IL-33, these findings when taken together could suggest that IL-33 activity on ST2+ cells may contribute to the development of severe cerebral malaria, while IL-33 activity may induce a therapeutic effect outside of the IL-33/ST2 axis." (PMID 32363166, 2020). "This group demonstrated using PbA-infected Treg-depleted mice receiving IL-33 or no treatment displayed significant cerebral malaria compared to mice receiving IL-33 with normal Treg function." (PMID 32363166, 2020). "Il-33 has been shown to be of importance for the protection against numerous infections including parasites and cerebral malaria and also during non-viral hepatitis and for cardiovascular system repair." (PMID 26214807, 2015). "In this review, we report the recent advances to our knowledge regarding the role of IL-33 and of its receptor ST2 in cerebral malaria, and in particular, we highlight the pivotal role that IL-33/ST2 signaling pathway could play in brain and cerebrospinal barriers permeability." (PMID 36362246, 2022).
Hepatitis (22 papers, 2012 to 2025). Inflammation of the liver. "HBV-associated hepatitis patients showed significantly higher serum IL-33 levels compared with healthy controls, which were also higher than non-HBV hepatitis patients." (PMID 40579434, 2025). "Biologically, the increased severity of hepatitis lesions in IL-33-deficient mice is associated with pronounced expression of TNFα and IL-1β and is accompanied by accumulation in the liver of activated NK cells." (PMID 31507607, 2019). "IL-33 production seems to moderate hepatitis severity, because: (i) IL-33-deficient mice have more heavily damaged livers than WT mice; (ii) injection of recombinant IL-33 renders less severe the hepatitis induced by ConA." (PMID 31507607, 2019). "We have recently demonstrated that hepatic release of IL-33 was associated with formation of large necrotic lesions during ConA-induced hepatitis and aggravation of disease pathology by activation of hepatic ILC2s expressing IL-5 and IL-13." (PMID 30213101, 2018). "The CD1d KO (NKT deficient) mice showed hepatoprotection against poly(I:C)-induced hepatitis in association with increased number of IL-33 expressing hepatocytes in CD1d KO mice than WT controls." (PMID 24058536, 2013). "To extend our findings to humans, we measured serum IL-33 levels in hepatitis patients and healthy individuals." (PMID 40579434, 2025). "IL-33 is markedly elevated in HBV+ hepatitis patients, and pitavastatin use significantly correlates with reduced risk of hepatitis and its associated HCC in patients." (PMID 40579434, 2025). "Adoptive transfer of exogenous IL-33-activated ST2+ Tregs before induction of hepatitis suppressed inflammatory T-cell responses and ameliorated disease pathology." (PMID 38571949, 2024). "Through transferring CD8+ T cell into Rag2−/− mice, perforin-based CD8+ T cell was found to initiate IL33/ILC2 axis to exacerbate the liver injury in ConA-induced hepatitis." (PMID 34654474, 2021). "Further studies are therefore needed with better characterized cohorts to conclusively address the role of IL-33 in these diseases (malaria and hepatitis)." (PMID 31849991, 2019). "An in-depth appraisal of the morbidity predictive value of plasma IL-33 during hepatitis should be pursued to validate this preliminary observation." (PMID 31849991, 2019). "Samples of participants missing any test result were excluded i.e., kato katz, malaria microscopy, hepatitis serology (B & C), or plasma IL-33." (PMID 31849991, 2019). "This indicates a carcinogenic role for IL-33-dependent ILC2s in the chronic setting of liver inflammation." (PMID 30999584, 2019). "Another focus of the relationship between IL-33 and hepatitis is the protective role of the IL-33/ST2 axis in concanavalin A- (Con A-) induced hepatitis." (PMID 29180837, 2017). "It is plausible that IL-33 is critical for dendritic cell proliferation as shown in a model of LCMV-induced hepatitis." (PMID 28607531, 2017). "For example, during concanavalin A (ConA)-induced hepatitis, IL-33 exerts protective effects and is mainly expressed by hepatocytes as a consequence of interaction with NKT cells and through the TRAIL pathway." (PMID 28611297, 2017). "In contrast, an increase in the number of neutrophils was observed in IL-33 KO mice after L2-MHV3 hepatitis." (PMID 28607531, 2017). "The majority of studies in this area support the view that IL-33 protects against Con A-induced hepatitis, and this protection involves a variety of immune cells (Treg, NK, and NKT cells) and molecules (IFN-γ and TRAIL)." (PMID 29180837, 2017). "The liver transcriptional expressions of CXCL1, CXCL2, CXCL3, CXCL5, CCL2, and CCL6 significantly increased in WT and IL-33 KO mice during L2-MHV3-induced hepatitis compared to those in control PBS-injected mice as soon as 48 h PI and at 72 h PI." (PMID 28607531, 2017).
Hepatitis (continued). "In the carbon tetrachloride-induced fibrosing hepatitis model, IL-33 expression is induced in sinusoidal cells and HSC, consistent with a perisinusoidal immunostaining in our study." (PMID 28611297, 2017). "This study revealed that mice defective of ST2 showed more severe hepatitis than the wild-type mice with higher number of inflammatory cell infiltration in the liver, and pretreatment of WT mice with IL-33 led to attenuation of the liver injury." (PMID 25892853, 2015). "In accordance, the number of IL-33 expressing hepatocytes following L2-MHV3 hepatitis increased significantly at 24, 28 and 32h of infection." (PMID 24058536, 2013). "Here we have shown that mRNA expression of IL-33 was over-expressed after L2-MHV3-induced hepatitis in mice." (PMID 24058536, 2013). "However, treatment of mice with exogenous IL-33 before induction of hepatitis ameliorated disease severity." (PMID 38571949, 2024). "On the one hand, strong cellular necrosis and, thus, a strong release of IL-33 might induce a pro-inflammatory function in ILC2s that cooperate with eosinophils to enhance acute liver inflammation." (PMID 30999584, 2019). "Interestingly, iNKT cell-deficient mice exhibited protection against poly(I:C)-induced hepatitis accompanied by an increased number of IL-33-positive hepatocytes compared with wild-type (WT) controls." (PMID 31507607, 2019). "In ConA-induced hepatitis, lack of IL-33 was associated with increased hepatic IL-1β expression and more severe liver injury, however, a possible link between the NLRP3 inflammasome and IL-33 was not analyzed." (PMID 30213101, 2018). "Divergent effects of the IL-33/ST2 axis have been described in ConA-induced hepatitis." (PMID 30213101, 2018). "Moreover, administration of IL-33 before induction of hepatitis expanded hepatic ST2+ Tregs and potently suppressed liver injury." (PMID 30213101, 2018). "More studies are needed to determine whether IL-33 protects or aggravates hepatitis induced by drugs and to elucidate the reasons for this discrepancy." (PMID 29180837, 2017). "However, the IFNγ was strongly induced in WT mice with less profound expression in IL-33 KO mice demonstrating that endogenous IL-33 regulated IFNγ expression during L2-MHV3 hepatitis." (PMID 28607531, 2017). "Interestingly, NKT-deficient mice were also resistant to Con A-induced hepatitis and no longer expressed IL-33 in liver cells following Con A administration, while IL-33 was overexpressed in normal mice." (PMID 29180837, 2017). "Changes in IL-33 expression in viral hepatitis and fulminant hepatitis triggered by toxins have been recently reported, suggesting that IL-33 may participate in different types of hepatitis." (PMID 29180837, 2017). "However, the opposite result was obtained in one study: treatment of rIL-33 exacerbated Con A-induced hepatitis, but pretreatment with an IL-33-blocking antibody exhibited a protective effect, likely by suppressing the late stage of T cell and NKT cell activation and decreasing IFN-γ production." (PMID 29180837, 2017). "As an alarmin, IL-33 is rapidly released from LSEC and vascular endothelial cells following carbon tetrachloride or Concanavalin A (ConA)-induced hepatitis to mediate a pro-inflammatory response." (PMID 31507607, 2019). "In contrast to these studies, a protective effect of IL-33 and ST2 in ConA-induced hepatitis was also described." (PMID 30213101, 2018). "In contrast, recombinant IL-33 (rIL-33) facilitated IFN-γ-producing γδ T and NK cells and inhibited IL-17+ γδ T cells, revealing a role of IL-33 in regulating innate IFN-γ production and antiviral responses in LCMV-infected hepatitis." (PMID 29180837, 2017). "In an Ad-induced hepatitis model, the expression of IL-33 and its receptor ST2 increased in the liver, and IL-33 induced the expansion of ILC2s strongly." (PMID 28659927, 2017).
Hepatitis (continued). "From this standpoint, IL-33 expression in LSEC significantly increases in patients with chronic HBV (CHB) infection, and is likewise highlighted in the hepatocytes of lesions/inflammatory foci in patients with the most severe form of hepatitis." (PMID 31507607, 2019). "The transcriptomic profile of 284 genes involved in inflammation, cell signaling, and remodeling showed that the expression of IL-1 family members, IL-1α, IL-1β, and IL-18, was not varied between WT and IL-33 KO mice following L2-MHV3 hepatitis." (PMID 28607531, 2017). "In liver pathology, we and others reported increased level of serum IL-33 and ST2 not only in acute and chronic hepatic failure in humans but also in patients chronically affected with hepatitis C and hepatitis B viruses (HCV and HBV) in correlation with liver damage." (PMID 28607531, 2017). "In ConA-induced hepatitis, NKT cells activate hepatocytes via TRAIL receptors to produce IL-33." (PMID 23653627, 2013). "Thus, we aimed to know the expression and regulation of IL-33 in Poly(I:C) and L2-MHV3 induced hepatitis in mice." (PMID 24058536, 2013). "The findings that blockage of IL-33 signaling through an anti-IL-33 antibody reduced NKT-cell activation and ameliorated disease pathogenesis and that pre-treatment with sST2-Fc attenuated liver injury further supported the pro-inflammatory role of IL-33 in ConA-induced hepatitis." (PMID 30213101, 2018). "The observation of decreased CXCR3 expression combined with the fall of lymphocyte number in the liver during hepatitis may explain that despite their induction in IL-33 KO context, these chemokines would not be able to interact with their target cells." (PMID 28607531, 2017).